CD1A (CD1a molecule)
Diseases named in the same sentence as CD1A in open-access papers (continued):
Sharing a sentence is not in itself a finding about the gene and the disease.
viral infections (3 papers, 2016 to 2025). "Similarly, in human immunodeficiency virus (HIV) and herpes simplex virus type 2 infections, CD1a cell numbers remained stable, reflecting the persistence of Langerhans cell populations during viral infections." (PMID 39997050, 2025). "The regulation of MHC antigen processing and presentation during viral infection involves four genes: AP3B1, B2M, CD1A, and CD1D." (PMID 41155393, 2025).
allergic disease (2 papers, 2016 to 2021). An immune response that occurs following re-exposure to an innocuous antigen, and that requires the presence of existing antibodies against that antigen. "Prior studies completed outside the context of CD1a have shown that individual patients with allergy to bee or wasp show a predisposition to show cross‐sensitization and cross‐reactivity." (PMID 26518614, 2016). "Furthermore, since mice lack Cd1a because of a massive genetic deletion of group 2 of lipid-presenting molecules, except for Cd1d, they constitute an excellent experimental model for analyzing the role of neoantigens in allergies caused by urushiols." (PMID 34711292, 2021). "In summary, we have shown increased frequency of venom responsive CD1a‐retricted T cells in allergic individuals, suggesting a role for these cells in allergic disease." (PMID 26518614, 2016). "However, CD1a‐reactive cells have not been investigated as a possible cause of the exaggerated response seen in venom allergic disease." (PMID 26518614, 2016). "Whether this reduction in IFN‐γ and IL‐13 producing CD1a‐reactive T cells is sustained beyond week 8 is unknown, however, it is noteworthy that it coincides with the induction of clinical tolerance, suggesting that wasp venom responsive CD1a‐reactive T cells may play a role in allergic disease." (PMID 26518614, 2016). "The role of CD1a‐reactive T cells in human allergic disease is unknown." (PMID 26518614, 2016). "Whereas all current approaches focus on the role of proteins or peptides in T‐cell response, these findings support a broad new view in which CD1a and nonpeptide antigens could participate in allergy." (PMID 26518614, 2016).
asthma (2 papers, 2016 to 2020). "The CD1C, TLR7, PTK2, CD1E, CD1A, and ERBB2 genes had a higher rate of engaging protein interactions in the PPI for the moderate-to-severe asthma phenotype." (PMID 32512817, 2020).
diabetes (2 papers, 2015 to 2022). "We excluded 3 targets (CD1a, 5HT 2B, DHOD) corresponding to 11 drugs projects, because they have no direct pathogenesis links to diabetes." (PMID 25946000, 2015).
diabetes insipidus (2 papers, 2016 to 2017). A disorder characterized by excretion of large amounts of urine, accompanied by excessive thirst. "In this case, he presented with diabetes insipidus, occipital, and liver involvement, with positive immunostaining (CD1a and S100) of liver issues, these finds were consistent with diagnose of multisystem LCH." (PMID 28248858, 2017).
emphysema (2 papers, 2021 to 2023). "The authors demonstrated that total CD4+ T cells from PBMC that were cocultured with CD1a+ from lungs of subjects with advanced emphysema, but not control subjects, secreted higher amounts of IFN-γ and IL-17A." (PMID 34956243, 2021). "Moreover, CD4+ T cells cultured with CD1a+ DCs from control, but not emphysema, differentiated into Treg cells, evidenced by an up-regulation of Foxp3 expression." (PMID 34956243, 2021). "Regarding the upregulated DEGs in COPD, CD109, B cell linker (BLNK), interleukin-1 receptor type 1 (IL1R1), CD1A, and carboxypeptidase A3 (CPA3) are related to T-helper cell type 2 (Th2) inflammation, but not to emphysema formation." (PMID 38203236, 2023).
eosinophilia (2 papers, 2011 to 2022). "Similar to the spleen, blood CD4 and CD8 T-cell counts, neutrophilia and eosinophilia were detected in the imiquimod-treated CD1a-Tg mice." (PMID 36477177, 2022). "As expected, BAL cell profile showed eosinophilia greater than 6%, mild neutrophilia and 8.1% [± 5.3] CD1a-positive cells." (PMID 22074767, 2011). "The clinical, immunological and functional features of our PLCH patients indicated prevalently obstructive lung function deficit, increased BAL CD1a+ cells together with neutrophilia and eosinophilia, in line with the literature." (PMID 22074767, 2011).
glioma (2 papers, 2019 to 2022). A benign or malignant brain and spinal cord tumor that arises from glial cells (astrocytes, oligodendrocytes, ependymal cells). "Moreover, high expression of ANXA1 were associated with high WHO grade, as well as high CD1a and PD‐L1 expression in gliomas." (PMID 35770335, 2022). "CD209 and CD1A did not demonstrate significant upregulation in any of the human glioma subtypes." (PMID 31475119, 2019).
Hemophagocytosis (2 papers, 2018 to 2024). Phagocytosis by macrophages of erythrocytes, leukocytes, platelets, and their precursors in bone marrow and other tissues. "Two cases were focally S100 positive (cases 10 and 13), and one of the S100-positive cases displayed some degree of hemophagocytosis (case 10); CD1a was always negative." (PMID 30084011, 2018).
HIV-1 infection (2 papers, 2021 to 2023). The type species of lentivirus and the etiologic agent of acquired immunodeficiency syndrome (AIDS). "Using primary human vaginal mucosa as well as different HIV-1 strains and isolates, we have shown that immature vaginal LCs highly expressing CD1a and langerin are poorly susceptible to HIV-1 infection and transmission in the vagina." (PMID 36841916, 2023). "Here we investigated the levels of HIV-1 infection of immature as well as of mature vaginal LCs (CD1a + and langerinhigh) after a 5-day exposure to various HIV-1 strains." (PMID 36841916, 2023). "In contrast, higher levels of HIV-1 infection were observed in mature CD1a + vaginal LCs." (PMID 36841916, 2023).
keloid (2 papers, 2021 to 2025). An irregularly shaped, elevated mark on the skin caused by deposits of excessive amounts of collagen during wound healing. "Here, we demonstrate that monocyte-derived inflammatory dendritic cells (CD1a+, CD11c+, CD14+) and activated CD4+ T lymphocytes (CD45 RO+) dominated the immune infiltration in keloids while associating with fibroblasts." (PMID 34502327, 2021).
lichen planus (2 papers, 2008 to 2014). A chronic, recurrent, pruritic inflammatory disorder of unknown etiology that affects the skin and mucus membranes. "High levels of Activin A were present in the upper epidermal layers and in the dermis of Lichen Planus biopsies in association with a marked infiltration of CD1a+ and Langerin+ cells." (PMID 18813341, 2008). "This is in line with our previous studies showing higher numbers of CD1a-expressing LCs in connective tissue of other oral inflammatory disorders (lichen planus and graft-versus-host disease) compared to healthy oral mucosa." (PMID 25350593, 2014).
lung adenocarcinoma (2 papers, 2021 to 2022). A carcinoma that arises from the lung and is characterized by the presence of malignant glandular epithelial cells. "Some studies have demonstrated that CD1A has antitumor effect and decreased CD1A is associated with early recurrence of lung adenocarcinoma." (PMID 35246970, 2022). "For the first time we could identify CD1A as a potential biomarker, whose reduced expression both on tumor and on tumor-infiltrating immune cells is associated with an early relapse after R0 resection of lung adenocarcinomas." (PMID 33953302, 2021). "We found CD1A|CXCL13, CD1A|S100A7L2, IFNA7|CMTM2, IFNA7|CSF3, CAMP|TFR2, this 5‐IRGPs were strongly associated with the prognosis of patients, all of which were protective factors for the prognosis of lung adenocarcinoma." (PMID 35246970, 2022). "Given the fact that CD1A immunohistochemistry is already performed routinely in many institutes of pathology in order to detect CD1A expressing Langerhans cells, implementation of CD1A staining in routine diagnostics for resected early-stage lung adenocarcinoma is easily feasible." (PMID 33953302, 2021).
metastatic melanoma (2 papers, 2021 to 2022). A melanoma that has spread from its primary site to another anatomic site. "In opposition to this observation, we detected a down-regulated level of CD1a molecules on moDCs upon exposure to both primary and metastatic melanoma cell lines." (PMID 36194602, 2022).
mycosis fungoides (2 papers, 2020 to 2023). Classical mycosis fungoides is the most common type of mycosis fungoides (MF), a form of cutaneous T-cell lymphoma, and is characterized by slow progression from patches to more infiltrated plaques and eventually to tumors. "A study on mycosis fungoides (MF) proved that the reduced presence of CD1a+ populations (DCs and Langerhans cells) was associated with a resistance to therapy." (PMID 36768258, 2023). "Increased numbers of CD1a- and CD1c-expressing dendritic cells have been reported previously in MF and folliculotropic mycosis fungoides (FMF), supporting a role that lipid may be an etiology of MF." (PMID 33299887, 2020).
oral cancer (2 papers, 2020 to 2022). "Moreover, other groups demonstrated in oral carcinomas that the decreased number of CD1a+ cells may be associated with cancer development." (PMID 36428652, 2022). "Our study investigated the distribution profile of the DCs in OSMF, OSMF-OSCC, OL, and OSCC and revealed a significant decrease of CD1a+ and CD207+ cells in oral cancer and OSMF, but not for CD303 positive cells." (PMID 31880289, 2020).
prostate carcinoma (2 papers, 2014 to 2015). A carcinoma that arises from epithelial cells of the prostate gland. "In a study comprising 38 prostate cancers, the presence of CD1a+ Langerhans cells was associated mainly with low-grade prostate carcinoma." (PMID 24772169, 2014). "In other study with prostate cancer patients, immunization led to recruitment of CD1a+ DCs, CD68+ macrophages, eosinophils, and neutrophils 4 days following inoculation; CD4+ and CD8+ cell affluence increased with immunizations." (PMID 25870600, 2015).
sarcoma (2 papers, 2016 to 2025). A usually aggressive malignant neoplasm of the soft tissue or bone. "Immunohistochemically, this sarcoma expresses S-100, CD1a, and vimentin, but is consistently negative for follicular dendritic cell markers." (PMID 26762155, 2016).
tongue cancer (2 papers, 2003 to 2022). A malignant neoplasm affecting the tongue. "Additionally, a higher number of CD1a cells adjacent to the tumor improved the survival of tongue carcinoma patients." (PMID 36428652, 2022).
type 2 diabetes (2 papers, 2017 to 2022). "We tested this hypothesis by analyzing a public data set for CD1 molecule expression among metabolically healthy adults, pre-diabetic adults, and adults with type 2 diabetes and we found that CD1a and CD1b are significantly downregulated in the diseased state." (PMID 28463985, 2017).
xanthoma (2 papers, 2024). A non-neoplastic disorder characterized by a localized collection of histiocytes containing lipid. "Besides CD68, supplementary markers such as S100, factor XIIIa + and CD1a are useful in separating xanthomas from other diseases." (PMID 38502367, 2024). "The xanthoma cells showed positive staining with CD68 in all patients while they were negative to S-100 and CD1a." (PMID 38504269, 2024).
acute myeloid leukemia (1 paper, 2014). Acute myeloid leukemia (AML) is a group of neoplasms arising from precursor cells committed to the myeloid cell-line differentiation. "Two acute myeloid leukemia (AML) samples, one chronic lymphoid leukemia and one normal lymph node were profiled and no CD1a+/CD3+ cells were identified." (PMID 25343480, 2014).
adenoid cystic carcinoma (1 paper, 2021). A malignant tumor arising from the epithelial cells. "In adenoid cystic carcinoma, association of intratumoral CD8+ with CD1a+ cells associates with less recurrence and higher survival rates." (PMID 33917958, 2021).
anal carcinoma (1 paper, 2016). "In an anal cancer cohort we studied the spatial distribution of dendritic cells (CD1a+), B cells (CD20) and Treg (FoxP3+) and found most of the dendritic cells and epithelial B cells to be non-functional, while stromal B cells and FoxP3+ cells were presumed to be functional cells." (PMID 27494875, 2016).
atopic asthma (1 paper, 2010). An asthma that is characterized by symptoms that are triggered by an allergic reaction caused by inhaled allergens such as dust mite allergen, pet dander, pollen and mold. "Moreover, inhaled corticosteroids reduced the number of CD1a positive DCs in bronchial biopsies of atopic asthma patients." (PMID 20307269, 2010).
bone sarcoma (1 paper, 2016). A sarcoma that arises from the bone. "Where there was a high number of CD68+ TAMs and CD3+ T lymphocytes in bone sarcomas, DC-SIGN-expressing DCs were noted; some of these cells stained for CD11c and S100 but they did not stain for CD1a." (PMID 27482375, 2016).
carcinoids (1 paper, 2019). "Furthermore, we found a correlation between the protein levels of DLL3 and CD1A (Pearson test p-value = 0.00034), providing additional evidence for the existence of a DLL3+ CD1A+ subgroup of carcinoids." (PMID 31431620, 2019).
celiac disease (1 paper, 2017). An autoimmune genetic disorder with an unknown pattern of inheritance that primarily affects the digestive tract. "The immunohistochemical staining for CD1a provided no positivity in any of the enrolled cases (NCGS as well as celiac disease and controls)." (PMID 29362561, 2017).
cervical dysplasia (1 paper, 2023). "One reason for our contrasting results could be the control exerted by miRNAs, as evidenced by McBee and co-authors in 2011; they reported a possible control of the CD1A gene by miR-344 in cervical dysplasia samples." (PMID 37053156, 2023).
chlamydial infection (1 paper, 2008). "In contrast, mDCs showed significant upregulation of CD1a during chlamydial infection and correlated significantly with IL-12 levels in Chlamydia positive fertile women." (PMID 18828896, 2008).
cognitive decline (1 paper, 2019). "In summary, we identified the associations of the three SNPs (rs16840041, rs2269714 and rs2269715) within CD1A with the increase in plasma NFL levels, faster decline of [18F] FDG and higher risk of cognitive decline among non-demented elders." (PMID 31295725, 2019).
dengue (1 paper, 2017). "We analyzed cell subsets by flow cytometry, and soluble mediators and antibodies by ELISA; the percentage of migratory CD1a+ dermal DCs was significantly decreased in the DSS patients, and skin CD8+ T cells were activated, but there was no accumulation of dengue-specific antibodies." (PMID 29079750, 2017).
ductal breast carcinoma (1 paper, 1999). "This study identified a population of CD1a+cells within the lymphoid cell infiltrate in human ductal breast carcinoma (n= 52), which was significantly different from normal breast tissue, in which only two out of nine cases expressed CD1a+cells (P= 0.0192)." (PMID 10070894, 1999).
dysplastic nevi (1 paper, 2017). "In that location mean values of dendritic cell number in dysplastic nevi versus invasive melanomas were, respectively, 14.72 versus 16.82 for CD1a, 32.00 versus 35.20 for CD1c, 1.0 versus 0.82 for DC-LAMP+, and 3.22 versus 4.00 for DC-SIGN+." (PMID 28331853, 2017).
eczema (1 paper, 2025). "In summary, the presence of CD14+ cells, and to some degree CD1a+ cells, seemed characteristic for eczema compared with Pso." (PMID 41009640, 2025). "The presence of CD1a+ cells (presumably LC) in the epidermis and dermis was quite similar in Pso and eczema (epidermis/dermis: 73/27% in Pso vs. 77/23% in eczema) (upper circles)." (PMID 41009640, 2025). "While in Pso a monocyte-derived DC (CD14+CD1a+CD11c+) predominated, possibly a Langerhans cell (LC)-like DC, eczema displayed a marker combination of a seemingly more differentiated monocyte-derived DC (CD14+CD63+CD163+), potentially a DC3 cell type." (PMID 41009640, 2025). "In addition, CD1a+ cells were twice as frequent in eczema compared with Pso and healthy controls (~150 cells/mm2 in eczema vs. ~80 cells/mm2 in Pso vs. ~85 cells/mm2 in healthy)." (PMID 41009640, 2025). "While Pso cells with DC markers maintained a CD14+, potentially LC-like phenotype (CD14+CD1a+CD11c+), cells in eczema displayed a marker combination that included CD163 and/or CD63, hinting at a more differentiated DC that may constitute a DC3 subtype, as previously suggested." (PMID 41009640, 2025). "Conversely, in eczema these cells additionally expressed CD63 and CD163 in various combinations with CD1a and CD11c." (PMID 41009640, 2025). "For eczema and Pso, the appearance of CD63 and/or CD163 in combination with CD14 and/or CD1a and/or CD11c in eczema was most discriminatory." (PMID 41009640, 2025). "Since numbers of CD1a+ and CD14+ cells revealed notable differences in Pso and eczema, we decided to characterise these cells in more detail by including additional markers." (PMID 41009640, 2025). "In summary, CD14+ positive cells harbouring DC markers (CD11c, CD1a) in combination with CD63 and/or CD163 were far more present in eczema compared with Pso." (PMID 41009640, 2025). "In summary, the appearance of CD63 and/or CD163 on CD14+ and/or CD1a/CD11c+ cells were most characteristic and distinctive for eczema skin, whereas the same cells were lacking CD63/CD163 in psoriatic skin." (PMID 41009640, 2025). "Conversely, CD1a+ cells (presumably LC) did not increase much in both diseases, only ~2.5-fold in eczema, namely from ~80 cells/mm2 to ~200 cells/mm2." (PMID 41009640, 2025).
End Stage Liver Disease (1 paper, 2025). Final stage of a liver disease when the liver failure is irreversible and LIVER TRANSPLANTATION is needed. "The main differentiator between LCH and other liver diseases that also result in end-stage liver disease is the presence of CD1a+ dendritic cells, especially proximal to the bile ducts." (PMID 40606814, 2025).
endometrial cancer (1 paper, 2023). Primary or metastatic malignant neoplasm involving the endometrium (mucous membrane that lines the endometrial cavity). "In agreement with other authors, we showed that expression of CD1a was stronger in endometrial cancer’s stroma and glands than in healthy endometrium." (PMID 36768258, 2023). "We hypothesized that the broader array of antibodies used (anti-CD83, -DC-LAMP, -CD1a, -CD1c, -CD123, and -DC-SIGN) would clarify the correlation between DCs’ infiltrates and the clinicopathological features of endometrial cancers." (PMID 36768258, 2023).
Erythema (1 paper, 2023). Redness of the skin, caused by hyperemia of the capillaries in the lower layers of the skin. "The appearance of a typical lesion progression after GAS infection showed marked erythema and scaling and expanded lesion site in the CD1a-Tg mice." (PMID 37267382, 2023). "CD1a-Tg mice with prior GAS infection displayed more pronounced pathological changes of scaliness, erythema, and significantly increased ear thickness." (PMID 37267382, 2023).
gallbladder cancer (1 paper, 2024). "The present study focused on the infiltration of CD1a-positive DCs (CD1a-DCs) into regional LNs in 70 cases of gallbladder cancer (GBC)." (PMID 39684473, 2024).
Gynecomastia (1 paper, 2023). Abnormal development of large mammary glands in males resulting in breast enlargement. "In the two patients in which CD68+/Cd1a(-) histiocytes were found in the breast, the gynecomastia was described to have been onset since the age of 50, with a progressive development of severe gynecomastia during the VI decade of life." (PMID 37046457, 2023).
haemophagocytic syndrome (1 paper, 2022). "Histiocytes phagocytose red cells in the haemophagocytic syndrome, and Langerhans cell histiocytes feature grooved and twisted nuclei with cd1a positive." (PMID 35131625, 2022).
helminth infection (1 paper, 2018). "It has been demonstrated that in vitro stimulation with helminth-derived antigens or helminth infection itself are able to decrease CD1a expression in MoDCs from both helminth-infected and healthy controls." (PMID 30687325, 2018).